APOE (apolipoprotein E)
Diseases named in the same sentence as APOE in open-access papers (continued):
Sharing a sentence is not in itself a finding about the gene and the disease.
dementia (continued). "Given that APOE ε4 allele carriers are more likely to have underlying AD pathology and progress to dementia faster, it was of interest to examine whether there were more or less carriers at this timepoint." (PMID 36879199, 2023). "In APOE ε4 carriers, there was only a significant association between type 2 diabetes and vascular dementia in ‘Model 1’, whereas there were no other significant associations between type 2 diabetes and dementia end-points." (PMID 37091584, 2023). "In epidemiological cohorts assessing patients without dementia using amyloid PET status or CSF profile, Aβ pathology was associated with APOE genotype, presence of cognitive impairment and suggested a 2- to 30- year interval between first development of Αβ positivity and onset of dementia." (PMID 37608222, 2023). "Moreover, among individuals experiencing a large BMI change, the presence of the APOE ɛ4 allele seemed to have an elevated risk of dementia." (PMID 35921193, 2023). "Therefore, we aimed to investigate the associations of APOE ε4/ε4 with fluid biomarkers in dementia and biomarker-diagnosed AD." (PMID 37065463, 2023). "To determine the association of plasma ApoE level with risk of incident dementia, we obtained hazard ratios (HRs) per 1-standard deviation (SD) lower ApoE level in 3031subjects using the Cox regression model adjusted for baseline age, sex, ethnicity, education, BMI, and the research site." (PMID 37666928, 2023). "There is evidence that APOE ε2 increases the rate of kidney disease progression compared to other APOE alleles, which could consequently accelerate the likelihood of developing dementia in this group." (PMID 37605228, 2023). "However, in subset of the GEM sample with lipoprotein subspecies data, the association of ApoE level in HDL with incident dementia and cognitive function was found to depend on the presence or absence of ApoC3." (PMID 37666928, 2023). "Although APOE ɛ4 and ɛ2 alleles are driving forces of AD and its related dementia, the burden of other risk alleles with smaller effects is also important for AD and dementia." (PMID 37950263, 2023). "The current study found similar associations between most RFs and dementia risk in men and women, and there was only moderate evidence indicating that APOE ε4 carriage was more strongly associated with dementia risk in men than women in our diverse populations." (PMID 36790027, 2023). "Large bodyweight gain and loss alike are associated with an almost 3-fold higher risk of dementia, which may be amplified by APOE ɛ4." (PMID 35921193, 2023). "In spite of this, they think the APOE ε4 allele cannot fully explain familial aggregation of EOAD as among APOE ε4 carriers as well as non-carriers the risk of EOAD increased significantly for those with a positive family history of dementia." (PMID 37589021, 2023). "When stratifying by APOE status, the associations were weaker amongst those with a higher genetic risk of dementia (ε4/ε4 or ε3/ε4), and stronger amongst those with a normal (ε3/ε3) and lower (ε2/ε2 or ε3/ε2) genetic risk of dementia." (PMID 37605228, 2023). "ApoE lipoproteins and the ApoE4 genotype are, with metabolic and environmental factors such as Hcy, tightly linked to the risk of vascular atherogenic changes, which can lead to dementia and AD." (PMID 37626897, 2023). "The experience with the APOE Ɛ4 haplotype and risk of dementia is thus exemplary." (PMID 38028602, 2023). "However, there is limited evidence available from diverse populations, as APOE associations with dementia seem to differ by race." (PMID 38115150, 2023). "We hypothesize that greater WMHs in cholinergic pathways would be associated with greater dementia severity and that the APOE e4 gene plays a facilitating role in the increased severity of clinical dementia." (PMID 36864910, 2023).
dementia (continued). "This study aimed to identify new genetic variants affecting plasma ApoE level as well as to test if baseline ApoE level is associated with cognitive function and incident dementia in a longitudinally followed cohort of the Ginkgo Evaluation of Memory (GEM) study." (PMID 37666928, 2023). "If confirmed, our findings suggest that the greatest population burden of dementia following HWI might be among those with advanced age or with APOE-ε4 risk alleles." (PMID 36622673, 2023). "Alternatively, the increased relative association could be due to the lower baseline risk of dementia in those with APOE ε2 allele." (PMID 37605228, 2023). "We hypothesize that adults who both gain and lose weight will be more likely to develop dementia compared with those with stable weight, and the presence of the APOE ε4 allele may worsen the impact of weight change." (PMID 35921193, 2023). "Consistent with associations described for innate immunity in previous literature, carriership of the APOE-ε4 allele may play an important role in the association between serum immunoglobulins and plasma biomarkers of dementia." (PMID 37936180, 2023). "Furthermore, the samples are too small to allow for further stratification for other interactions, such as the effects of genetics such as the APOE ɛ4 allele, which appears to be important in the impact of omega-3 fatty acids on dementia outcomes." (PMID 37509132, 2023). "APOE is the major lipid and cholesterol carrier in the CNS; it is important in lipoprotein metabolism in the brain and in the periphery, and is implicated in dementia and in ischemic heart disease." (PMID 36982820, 2023). "Important biological questions are whether and how genetically determined ApoE level can affect the risk of AD or dementia and whether the observed variation in plasma ApoE level is also reflected in the CNS." (PMID 37666928, 2023). "Our results show that the TOMM40 locus may have a role in the risk of dementia, even in non APOE Ɛ4 carriers." (PMID 38028602, 2023). "This may explain the discrepant results of the reported association studies of ApoE level with dementia." (PMID 37666928, 2023). "Fourth, we were able to show that the APOE e4 allele affects age-related cognitive decline independently of possible cognitive impairment, dementia, and deaths to follow up, suggesting that this relationship is present, not just in dementia and AD, but in cognitively “healthy” individuals." (PMID 36481934, 2023). "Given the role of APOE e4 in AD, this may modulate the risk of dementia via AD pathology in at least a subset of the LBD-D cases; however, previous work has been inconsistent." (PMID 37987016, 2023). "Lower plasma ApoE level has also been suggested to be a risk factor for incident dementia." (PMID 37666928, 2023). "Thus, there is compelling evidence that genetic factors, including PRS and APOE-ɛ4, influence the risk of developing dementia." (PMID 37834213, 2023). "Beyond helping to disentangle the genetic architecture of LOAD, such knowledge may improve precision in predicting the risk of dementia and enable effective sex‐ and APOE‐stratified preventive and therapeutic interventions for LOAD." (PMID 37621137, 2023). "Genome-wide association studies (GWAS) and meta-analyses have exposed the ε4 allele variant of the APOE gene (APOE ε4) as a contributing risk factor for increased rate of cognitive decline, worsened cognitive impairment and/or earlier onset of dementia in synucleinopathies with cognitive features." (PMID 37482615, 2023). "Two of the greatest non-modifiable risk factors for development of AD (aside from autosomal dominant familial AD gene mutations) are aging and APOE status, and two of the greatest modifiable risk factors for AD and related dementias are untreated major depressive disorder (MDD) and obesity." (PMID 37304012, 2023).
dementia (continued). "In fact, our analyses estimated that the percent excess risk of APOE-ε4 on other causes of mortality risk explained by the dementia diagnosis was 24%, which increased to 34% when we limited the sample to adults who were aged ≤75 years old and 32% when the analyses were restricted to women." (PMID 37434484, 2023). "According to previous evidence, the association of APOE-ε4 with cognition and dementia seems to be mediated by an increased burden of AD-pathology: neurofibrillary tangles (NFT) formed by hyperphosphorylated tau proteins and neuritic plaques (NP) composed of β-amyloid peptides." (PMID 38115150, 2023). "In this population-based cohort study of Swedish older adults, we aimed to (a) investigate the associations between BMI/weight changes and dementia risk and (b) assess whether APOE ε4 carrier status modulates these associations." (PMID 35921193, 2023). "Moreover, AD risk factors (e.g., APOE genotype) modulate the prevalence of microorganisms in dementia patients." (PMID 37496074, 2023). "Yet the alleles of APOE regulate the risk of dementia in the same way for each of these scenarios, suggesting–as argued above and previously–that genetically determined vessel fragility is a third common factor in the pathogenesis of dementia." (PMID 36950132, 2023). "Moreover, we explored the influence of APOE variants on the atrophic trajectories of target brain regions from CN to dementia stages." (PMID 37323144, 2023). "The independent and additive associations of walking pace and grip strength on dementia risk and the potential modifying effects of age, APOE phenotypes, and other dementia risk factors on the walking pace and dementia relationships demand further clarification." (PMID 36624486, 2023). "In addition to their relevance to dementia, plasma apoE levels have also been implicated in ischemic heart disease." (PMID 37400888, 2023). "As variants in APOE, which encodes a lipid transport protein, are the most significant determinant of genetic risk for dementia, we first determined whether lipid levels were significantly affected by APOE genotype." (PMID 37726834, 2023). "Furthermore, neuroimaging studies based on Aβ PET proved that APOE ε4 carriers suffered a higher risk of Aβ plaque in cognitively normal elders and dementia." (PMID 37323144, 2023). "When we account for the APOE haplotype (the strongest genetic risk factor associated with AD) in the model, our analyses reveal that having the APOE ε4/ε4 variant and being categorized in the weight loss group are both important risk factors of dementia." (PMID 37628615, 2023). "Additionally, we estimated the association between vitamin D and the incidence of dementia stratified by APOE e4 genotype." (PMID 37246226, 2023). "The developed assay was applied to investigate the impact of PRS and the ɛ alleles of the APOE on dementia risk among the residents of the Moscow region in the Russian population, utilizing a sample of 348 individuals diagnosed with dementia and 519 cognitively normal participants." (PMID 37834213, 2023). "Having used mediation analyses, we further assessed the relative magnitude of different pathways by which APOE-ε4 status, polygenic predisposition to longevity, and diagnosis of dementia influenced all-cause mortality, and specific causes of mortality, in older adults from the general population." (PMID 37434484, 2023). "Here, the mediation hypothesis was that APOE-ε4 presence increases the risk of all-cause mortality, and cause-specific mortality, via dementia diagnosis." (PMID 37434484, 2023). "Lastly, tea intake or consumption could reduce the risk of all-cause dementia to a greater degree among populations with less physical activity, older age, APOE carriers, and smokers." (PMID 37483967, 2023). "PRS and APOE-ɛ4 were significant genetic risk factors for dementia." (PMID 37834213, 2023).
dementia (continued). "While the TOMM40 gene biology suggests that it could contribute independently to the risk of dementia, its proximity to the APOE gene could lead to a spurious association in genetic analyses." (PMID 38028602, 2023). "Depression prevalence among MCI patients may be as high as 32% and is considered a risk factor for dementia progression and accelerated rate of cognitive deterioration (possibly moderated by APOE ε4 carriership)." (PMID 36900708, 2023). "We also explored APOE, a gene harboring a common variant linked to dementia." (PMID 35314672, 2022). "As the global prevalence of dementia is quickly rising, there is an unprecedented need to characterise the impact of genetic predisposition (e.g., Apolipoprotein E (APOE) polymorphism) and modifiable risk factors on ADRD-vulnerable brain structures before the onset of cognitive decline." (PMID 36512526, 2022). "Previous studies have yielded mixed results with regard to whether the associations between sleep problems and dementia in older adults vary by APOE ε4 allele status." (PMID 34979998, 2022). "Intriguingly, ApoE ε4 homozygotes have an increased risk of delirium, in addition to dementia." (PMID 35055344, 2022). "The interplay between other diseases and dementia needs further clarification, and more studies need to address these associations and how APOE and BIN1 might influence these pathologies." (PMID 39081475, 2022). "We found that the association between glucosamine use and dementia differed by APOE genotype." (PMID 36514123, 2022). "With the adjustment for demographics, APOE ε4 genotype, sun-exposure time, and blood collection season in Model 1, serum 25(OH)D concentrations were inversely associated with the risk of all-cause dementia in a dose-dependent manner (Ptrend < 0.001)." (PMID 35025861, 2022). "Here, we hypothesized that in participants aged 65 years and older, higher RBC levels of DHA are associated with lower risk of incident AD and of all-cause dementia, and that an interaction with APOE-ε4 carriership exists." (PMID 35745137, 2022). "Our findings reiterate that increasing intake of fruits and vegetables to at least 5 portions a day may lower the risk of dementia and AD independently from the genetic propensity for this disease and the APOE-ε4 status." (PMID 35093034, 2022). "Additionally, CCSMA features, like APOE genotype, APOE ε4 copy number, and any variant of APOE ε4, are genetic markers and indicate an influence on dementia." (PMID 35368316, 2022). "This further supports subtle but unique effects of APOE genotype to the cerebral cortex at a young age that may predispose for AD and dementia later in life." (PMID 35370604, 2022). "We hypothesize that short and long sleep duration, poor sleep quality, low sleep efficiency, prolonged sleep latency, and EDS are associated with dementia in older adults, and that the associations may vary depending on demographic factors and APOE ε4 status." (PMID 34979998, 2022). "Thus, the studies on genetic factors associated with dementia, particularly APOE genotype, were facilitated by the availability of registries data." (PMID 35197840, 2022). "In addition, we identified APOE polymorphisms in the study participants because their association with dementia risk is well known." (PMID 36421848, 2022). "In addition, a previous study has reported that the apolipoprotein E alleles, ApoE-ε4 allele, a crucial risk factor for the development of dementia, was detected in both patients with DM and patients with AD." (PMID 35765060, 2022). "Besides monogenic causes, we suspect a polygenic/multifactorial etiology in around half of the families based on APOE and rare variants in dementia-related genes." (PMID 35650585, 2022). "Hence, they utilize established risk stratification approaches, using factors such as family history of dementia (FHD) or apolipoprotein (APOE) ε4 genotype, which is the main genetic risk factor for sporadic late onset AD—LOAD." (PMID 35279756, 2022).
dementia (continued). "Third, we performed subgroup analysis by ApoE-ε4 carrier status for all-cause dementia and AD." (PMID 36517471, 2022). "The variability of the protective effect of physical activity on dementia risk when stratifying participants by ɛ4 status might be taken to suggest that APOE ɛ2 is driving the relationship between physical activity and cognitive performance." (PMID 36512526, 2022). "The homeostasis of fatty acids and related pathways is known to be impaired in cognitive decline and dementia, but the relationship between these metabolic disturbances and common risk factors, namely the ɛ4 allele of the apolipoprotein E (ApoE-ɛ4) gene and sex, remains elusive." (PMID 34980257, 2022). "The APOE gene is also associated with the risk of vascular, Lewy Body and other forms of dementia." (PMID 36477264, 2022). "High genetic risk for dementia was based on presence of 1 or 2 apolipoprotein (APOE) ε4 alleles." (PMID 36125811, 2022). "Sleep characteristics associated with dementia are poorly defined and whether their associations vary by demographics and APOE genotype among older adults are unclear." (PMID 34979998, 2022). "The population in our study was relatively younger (mean age = 62.71 years), and the influences of the APOE ε4 allele on dementia were suggested different, attenuating with increasing age, which might explain part of the non-significant interactions." (PMID 35619174, 2022). "Independent from pre-existing dementia or other comorbidities, a recent UK study reported that the APOE ε4 allele is linked to increased risk of infection and mortality due to COVID-19, although the biological mechanisms involved in this association remain to be elucidated." (PMID 35055344, 2022). "Third, after excluding ε2/ε4 participants (because of the known protective effects of the ε2 allele), we observed an interaction DHA × APOE-ε4 carriership on incident AD and all-cause dementia, with a trend towards a greater benefit of DHA in ε4 carriers than in non-carriers." (PMID 35745137, 2022). "We observed a joint effect of glucosamine use and APOE ε4 genotype on risk of dementia." (PMID 36514123, 2022). "In contrast, the presence of one or two copies of the APOE-ε2 allele is associated with a lower risk of AD and an older mean age of dementia onset; therefore, it has been hypothesized that the apoE2 protein could be protective against AD." (PMID 36324176, 2022). "Given the well-established association between psychosis and dementia in PD, as well as the relationship between advanced disease and the manifestation of psychotic symptoms, it has been suggested that APOE ε4 may increase the risk of PDP." (PMID 35741861, 2022). "Further, we used our new humanized APOE mouse models to test our hypothesis that APOEε3/ε4 mice show characteristics that may modify risk for dementias that are distinct from APOEε4/ε4 mice." (PMID 35370604, 2022). "As expected, type 2 diabetes, age and ApoE-ε4 were significant predictors of subcortical structural atrophy and cognitive decline, which is consistent with known risk factors for dementia." (PMID 35173604, 2022). "We speculated that PPIs might affect Aβ metabolism and synergize with the APOE ε4 to promote Aβ accumulation and increase dementia risk." (PMID 36045363, 2022). "Besides, the impacts of age and the apolipoprotein E4 (APOE4) carrier status on dementia risk was well studied." (PMID 36476644, 2022). "The main goal of this study was to assess whether disrupted RSFC may underlie impaired visuomotor abilities in individuals with specific dementia risk factors (positive family history of dementia, or presence of the APOE ε4 allele)." (PMID 36533177, 2022). "As we all know, the uncontrollable and common risk factors of dementia include aging, a first-degree family history of dementia, carrying APOE ε4 allele, and being a female, especially after the age of 80 years; among these, the strongest risk factors are advanced age and APOE ε4 allele carrier." (PMID 35983224, 2022).